RNU6-1146P (RNA, U6 small nuclear 1146, pseudogene)
Gene: Small nuclear RNA gene on chromosome 20 (56,667,430 to 56,667,531, forward strand). Ensembl gene ENSG00000252091.
Homologues: Orthologues: chimpanzee U6 (93% identical), macaque U6 (86% identical), zebrafish U6 (83% identical), zebrafish U6 (82% identical), pig U6 (78% identical). Paralogues in human: RNU6-842P (87% identical), RNU6-1117P (86% identical), RNU6-1011P (85% identical), RNU6-12P (85% identical), RNU6-13P (85% identical), RNU6-25P (85% identical), RNU6-26P (85% identical), RNU6-32P (85% identical), RNU6-33P (85% identical), RNU6-38P (85% identical), RNU6-41P (85% identical), RNU6-468P (85% identical), and 1285 more.